CD34 (CD34 molecule)
Diseases named in the same sentence as CD34 in open-access papers (continued):
Sharing a sentence is not in itself a finding about the gene and the disease.
sarcoma (continued). "We extracted the expression profiles of four sarcoma-related tumor biomarkers, MDM2, CDK4, CD34, and TLE1, from the cohorts TCGA-SARC and GSE21050 and analyzed their expression profile in each IMS." (PMID 36153483, 2022). "Immunohistochemical stains for epithelial markers (pancytokeratin), endothelial markers (CD34 and CD31), and other sarcoma markers should help in making the correct diagnosis." (PMID 23607567, 2013). "Since CD34 is a marker for lipomas and lipoma-like sarcomas, further analysis of SCL typically shows negative staining for desmin, RB1, MDM2, and SMA." (PMID 40980795, 2025). "Immunohistochemistry tests for desmin, vimentin, α‐SMA, CK, leukocyte common antigen (LCA), CD34, human melanoma black 45 (HMB45), epithelial membrane antigen (EMA), and S100 are performed in sarcomas to differentiate other tumor types and make a final diagnosis." (PMID 36093467, 2022). "Apart from CD34, there are no additional diagnostic immunomarkers for DFSP, and thus, there is the need to identify more sensitive and specific markers for this sarcoma." (PMID 33445443, 2021). "The TPR-NTRK1 fusion-positive tumor was a CD34-positive, dural-based, high-grade undifferentiated sarcoma with features that did not fit the classifications of existing types of sarcoma." (PMID 32957984, 2020). "Our patient's immunohistochemistry test results were negative for cytokeratin, vimentin, and CD-31 and CD-34, allowing us to exclude a likely diagnosis of adenocarcinoma, sarcoma, or vascular tumor, respectively." (PMID 21801379, 2011). "Staining for S100, actin, caldesmon, desmin, and CD34 was focal and nonspecific, indicating that the tumors could not be assigned to a particular differentiated sarcoma subtype." (PMID 37332046, 2023). "The TPR-NTRK1 fusion sarcoma was positive for CD34 and nestin but negative for S100 protein." (PMID 32957984, 2020). "Firstly reported by Penner in 1951 to represent a component of intermediate to high grade sarcoma, with more spindle cells, greater number of nuclei and increased mitotic rate compared to "classic" DFSP(median: 20 vs. 2 mitoses/HPFs), immunohistochemically demonstrating a decrease of CD34." (PMID 21294902, 2011). "The absence of lineage-specific markers, including EMA, CD34, CD31, myogenic markers (MyoD1, myogenin), melanocytic markers (HMB-45), and lymphoid markers (CD45), helped exclude alternative diagnoses such as sarcomas and hematologic malignancies." (PMID 41552210, 2025). "Various markers, such as desmin, S100protein, CD31, CD34, epithelial membrane antigen (EMA), cytokeratin, and E-cadherin, are used to rule out other types of sarcomas." (PMID 41446455, 2025). "The difference from LCA is that the sarcoma is positive for CD8 and CD34, while negative for CD21 and FVIII antigen, and high ki-67 proliferation index." (PMID 38552075, 2024). "As they can be of a very heterogeneous origin, there are no specific immunohistopathological markers of intimal sarcomas but a panel including endothelial differentiation markers CD31, CD34, and von Willebrand factor may increase sensitivity." (PMID 40034398, 2025). "In contrast to neuroblastic tumors, soft tissue tumors and other extraosseous sarcomas—n = 20 (18%), with 19/20 infiltrated by MFC—had a common CD56++ CD271++ CD81++ phenotype in the absence of CD45, CD34, and EpCAM expression, with three distinct (heterogeneous) phenotypic profiles." (PMID 34638431, 2021).
hepatocellular carcinoma (37 papers, 2008 to 2025). A malignant tumor that arises from hepatocytes. "A very recent study showed that higher pre-treatment levels of CD133+/CD34+/CD45dim cells (called circulating progenitor cells in that study) were associated with the worst outcome of suntinib therapy in hepatocellular carcinoma." (PMID 20010948, 2010). "Importantly, increased CD34 expression has been associated with risk of hepatocellular carcinoma (HCC) in MASLD." (PMID 40738518, 2025). "The results showed that the expression of CD147 was positively correlated with metalloproteinase-2, vascular endothelial growth factor and microvascular density CD34 in hepatocellular carcinoma patients." (PMID 37090718, 2023). "In recent years, an increase in CD34 expression, Ang II, and vascular endothelial growth factor has been documented in patients with severe hepatocellular carcinoma." (PMID 37241170, 2023). "To explore the potential molecular mechanism by which sja-miR-61 inhibited in vivo growth of hepatoma, we detected the expression levels of both Ki67 and CD34 using immunohistochemistry (IHC)." (PMID 34221971, 2021). "HepPar-1, CD10 and CD34 demonstrated 86%, 72%, 86% sensitivity and 100% specificity respectively for hepatocellular carcinoma; CK7&CK19 showed 100% sensitivity for cholangiocarcinoma, MOC 31 showed 90% sensitivity and 100% specificity for metastatic carcinoma." (PMID 34514559, 2021). "Treatment with polysaccharide from ASP in an orthotopic hepatocellular carcinoma model of Wistar rats significantly reduced CD34 and VEGF expression in tumor tissues, indicating an anti-angiogenic function for ASP in vivo." (PMID 34336674, 2021). "Circulating EPC elevation with phenotype CD144+/CD34+/CD133+/CD45− was found in hepatic carcinoma patients and seemed to be positively correlate with tumor burden, suggesting potentials in cbLB biomarker translation (see HSC)." (PMID 32218149, 2020). "Special stains, such as reticulin stain and CD34 immunostain, are very helpful in the diagnosis of well differentiated hepatocellular carcinoma (HCC)." (PMID 21338527, 2011). "Besides being involved in inflammation, COX-2 was positively correlated with the expression of CD34 in hepatocellular carcinoma, denoting its potential implication in tumour angiogenesis." (PMID 38388410, 2024). "Furthermore, CD34+ cell populations isolated from PLC/PRF/5 liver carcinoma have the ability to generate multiple types of liver cancer in mice." (PMID 37241170, 2023). "An atypical resection of the VIIth hepatic segment was performed and the histohistological examination and imunohistochemistry (Hep Par-a positive, Glypican3 positive, CD34 positive) revealed a moderately differentiated hepatocellular carcinoma (G2), pT2 N0 M0 L0 V1 R0." (PMID 37488645, 2023). "In vitro experiments showed that stable knockout of ANXA5 reduced the proliferation, migration, invasion, and lymph node adhesion of hepatoma Hca-P cells by inhibiting CD34 and VEGF3 increased the adhesion behavior between cells, and reduced tumorigenicity and malignant tumorigenesis in mice." (PMID 35992798, 2022). "The hepatic mRNA expression of ACE2 is negatively correlated with that of CD34, an angiogenesis marker, in hepatocellular carcinoma (HCC)." (PMID 39622780, 2024). "The purpose of this study was to determine and compare MVD with CD105 and CD34 antibodies in small hepatocellular carcinomas (HCC), regenerative and dysplastic liver nodules." (PMID 24507660, 2014). "In this study, immunohistochemical analyses for endocan, CD34 and CD105 were performed on paraffin-embedded samples of 66 pituitary adenomas, five normal pituitaries, and five primary hepatic carcinomas." (PMID 26809958, 2016). "In 2013, this group reported that the versican 3′UTR induces the development of hepatocellular carcinoma (HCC) and demonstrated that the versican 3′UTR can increase the expression of versican, CD34, and fibronectin via a ceRNA mechanism in HCC cells." (PMID 26872371, 2016).
hepatocellular carcinoma (continued). "These CD34-positive MSC exhibited a greater expression of angiogenesis-related genes, including fibroblast growth factor 7 and hepatoma-derived growth factors." (PMID 21151968, 2010). "Angiogenesis, as defined by the extent of sinusoidal capillarisation detected by CD34 antibodies, increases with progression towards hepatocellular carcinoma (HCC) commencing at the low-grade dysplastic nodule stage with a concomitant increase in VEGF expression." (PMID 18941463, 2008). "This detrimental effect of reduced CD34-MVD on prognosis has been found not only in NSCLC but also in other malignancies, such as kidney cancer, bladder cancer, ovarian cancer, intrahepatic cholangiocarcinoma, and hepatocellular carcinoma." (PMID 39906069, 2025). "The expression of CD34 and CD105 in hepatocellular carcinomas (HCC) and hepatic precancerous lesions has been reported—although the results for CD105 are controversial—but to the best our knowledge, CD105 has not been previously investigated in dysplastic nodules (DN)." (PMID 24507660, 2014). "In hepatocellular carcinoma (HCC), a significant number of CAFs highly express CD90, which correlates with angiogenesis markers (CD105, CD34, and CD31) and is related to poor prognosis in HCC patients." (PMID 37143134, 2023). "In patients with hepatocellular carcinoma (HCC) recurrence, the majority of hepatic stem/progenitor cell (HSC/HPC) biomarkers are overexpressed, including cytokeratin 19, ABCG2, CD133, Nestin, and CD44, and angiogenesis agents CD34, VEGF, and PD-ECGF." (PMID 32466488, 2020).
myeloid leukemia (36 papers, 2010 to 2025). A clonal proliferation of myeloid cells and their precursors in the bone marrow, peripheral blood, and spleen. "Within AMKL, transient abnormal myelopoiesis (TAM) and myeloid leukemia associated with DS (ML-DS) show higher frequencies of CD34+/CD117+ leukemic blasts compared to other AMKL subgroups." (PMID 39594810, 2024). "We obtained cryopreserved bone marrow aspirates (BM) from healthy donors and AML patients and performed flow cytometry using a myeloid leukemia panel (CD45/CD34/CD117/CD33/CD13/HLA-DR)." (PMID 40269321, 2025). "We then compared the level of CARM1 protein expression and CARM1-Y149 and -Y334 phosphorylation in 14 myeloid leukemia cell lines, using normal human CD34+ cord blood (CB) cells as control." (PMID 38649367, 2024). "For chronic (K562) and acute (KG-1) myeloid leukemia cells, the CD34, and CD38 antigens were selected for analysis." (PMID 35053549, 2022). "In line with the previously published data, we observed that CK2 is overexpressed in myeloid leukemia cells and primary cells with various cytogenetic features compared to normal hematopoietic cells (CD34+ HSC)." (PMID 33807974, 2021). "KG1a is a CD34 positive AML cell line described to be stem-like while U937 is a pro-monocytic human myeloid leukemia cell line." (PMID 33842460, 2021). "Cancer stem cells were first identified in myeloid leukemia with the cell surface marker combination of CD34+ and CD38-." (PMID 30237856, 2018). "The validity of this approach has already been demonstrated in the myeloid leukemia field, where reintroduction of C/EBPα in CD34 + leukemic cells impaired their self-renewal capacity and enhanced myeloid differentiation." (PMID 29070836, 2017). "Of note, both KG-1a and KG-1 cells express human hematopoietic stem and progenitor cell antigen CD34, and are considered as the most primitive myeloid leukemia cell lines." (PMID 27801668, 2016). "TWIST-1 knockdown impaired stem/progenitor cell colony-forming capacity of primary myeloid leukemia CD34+ cells." (PMID 26023795, 2015). "The presence of myeloid specific markers, such as MPO, CD117, CD99 and CD34 should be helpful in making a diagnosis of myeloid leukemia first presenting in skin or cutaneous myeloid sarcoma." (PMID 23388086, 2013). "In the five myeloid leukemia cell lines, miR-92a expression ranged from 10.2 to 25 (mean ± SD, 15.1 ± 6.665) and was significantly higher than in CD34-positive cells (mean ± SD, 7.814 ± 2.360; P = 0.0251)." (PMID 21182798, 2010). "One of the first potentially detected CSCs was CD34+ CD38- myeloid leukemia cells." (PMID 33424978, 2020). "To determine genome-wide rearrangements of H3K9me2, we conducted ChIP with anti-H3K9me2 and several control antibodies with normal human granulocytes, normal bone marrow CD34+ hematopoietic progenitors, and K562 human myeloid leukemia cell line (see experimental flowchart in Fig A in S1 File)." (PMID 28301528, 2017). "Importantly, TWIST-1 expression in CD34+CD38− immature cells from myeloid leukemia patients (n = 6) was significantly higher compared with cord blood (CB) (n = 5)." (PMID 26023795, 2015). "Down-modulation of TWIST-1 in myeloid leukemia CD34+ cells impairs their colony-forming capacity." (PMID 26023795, 2015). "Furthermore, in functional xenograft assays, NSG mice engrafted with more immature CD99-positive CD34+CD38− AML LSCs rapidly developed fatal myeloid leukemia, whereas engraftment with CD34+CD38− CD99-negative cells resulted in normal lympho-myeloid development." (PMID 40427525, 2025). "We also examined the ability of our 123b-33bcCAR to eliminate specific cell populations including LSCs (CD123+CD34+CD38−) in the PT3 sample and myeloid leukemia bulk disease (CD34variableCD33+) in the PT4 sample." (PMID 29515236, 2018). "LSCs have been reported to demonstrate a CD34+CD38− phenotype, reflected by the acute immature myeloid leukemia cells KG1a cell line, which expresses high level of CD34 and lacks CD38." (PMID 26557682, 2015).
myeloid leukemia (continued). "Likewise, depending on the subtype of myeloid leukemia, LSC may reside within the CD34+/CD38− fraction of the clone but also in the CD34+/CD38+ or even in CD34− cell populations." (PMID 25886184, 2015). "Remarkably, the authors have demonstrated that the viability of healthy CD34-positive cells is not affected by DPI, suggesting that this compound might be safely used in the treatment of myeloid leukemia." (PMID 35626090, 2022). "Although its expression level was not restricted to the CD34+CD38- fraction, immunotherapy targeting PEPP2 might contribute to eradicating residual LSCs in myeloid leukemia patients." (PMID 26784514, 2016).
vascular tumors (36 papers, 2011 to 2026). "CD34 is a highly glycosylated transmembrane glycoprotein and associated with the origin of vascular tumors." (PMID 30819247, 2019). "Vascularity, measured by CD34 staining, grouped tumours into a vascular group of tumours (ccRCC, 12.6% positivity; oncocytoma, 10.4%; and chRCC, 7.1%) and non-vascular tumours (pRCC, 2.8%)." (PMID 41495369, 2026). "On immunohistochemistry, CD31 and CD34 positivity indicates hemangiomas, lymphangiomas, and other benign vascular tumors, and the lymphatic endothelial marker D2‐40 negativity and lymphocyte deficiency help to rule out lymphangiomas." (PMID 41584391, 2026). "CD34 is a stem/progenitor cell and endothelial marker, also seen in fibroblasts and vascular neoplasms; its expression in the stromal cells of cardiac myxomas supports a mesenchymal origin." (PMID 40630762, 2025). "CD31 is a transmembrane glycoprotein that is expressed by platelets, megakaryocytes, and endothelial cells and was found to have less background staining than CD34 in feline vascular neoplasms." (PMID 36807589, 2023). "All of the tumors showed strong expression of CD31 or CD34 via immunohistochemistry, indicating that they were vascular tumors." (PMID 26840265, 2016). "CD34 is also reported to be expressed by >90% of vascular tumors, however, this marker is much less specific and is expressed by several other soft tissue tumors." (PMID 24932310, 2014). "Anti-CD34 antibody is a highly sensitive marker for endothelial cell differentiation and has also been studied as a marker for vascular tumors." (PMID 24386936, 2014). "Malignant vascular tumors are characterized by CD34 staining." (PMID 39420880, 2024). "Furthermore, CD34 negativity is observed, which differentiates it from other vascular tumors such as epithelioid hemangioendothelioma or epithelioid angiosarcoma." (PMID 31311568, 2019). "During the development of human vascular tumors, over-expression of CD34 could promote tumor angiogenesis." (PMID 29228721, 2017). "Comparison with other pediatric vascular tumors revealed that the neoplastic cells of KHE expressed Prox1+, CD31+, and CD34+." (PMID 41303262, 2025). "Immunohistochemical staining, typically positive for vascular markers such as CD34 and CD31, further aids in distinguishing intraosseous hemangiomas from malignant vascular tumors." (PMID 39669857, 2024). "On performing immunohistochemistry for ruling out differential diagnosis, vascular markers CD31, CD34 and Factor VIII are specific in differentiating between carcinomas and vascular neoplasms." (PMID 38291481, 2024). "Immunohistochemical staining was negative for GATA-binding protein 3 (GATA-3), pan-keratin, and epithelial membrane antigen (EMA), and positive for CD34 and CD31, supporting the diagnosis of a benign vascular tumor." (PMID 39669857, 2024). "The immunophenotype in all cases was consistent with the known character of this vascular tumour, displaying positivity for the typical endothelial cell markers CD31, CD34 and ERG." (PMID 37686662, 2023). "In cats, CD34 and CD31 have both been utilized in the assessment of feline endothelium, specifically vascular neoplasms." (PMID 36807589, 2023). "Immunohistochemically, vascular endothelial markers such as Von-Willebrand factor, CD34, CD31 and Fli-1 are commonly positive in most of tumors at varying intensities in each case, which help identify and diagnose the tumor as a type of vascular neoplasms." (PMID 24063649, 2013). "CD34 is expressed in more than 90% of vascular tumors, so although it is relatively sensitive, it is not very specific to EHE." (PMID 32812146, 2021). "According to the nature of vascular tumours, they were positive for CD31 and CD34 staining." (PMID 32591592, 2020). "However, the cells are positive for CK and they lack reactivity to the usual vascular markers CD31, CD34, factor VIII, which exclude vascular tumors." (PMID 25487416, 2014). "CD34 was a sensitive marker of vascular tumors but not specific enough." (PMID 37601682, 2023).
vascular tumors (continued). "CD31 in fact is a marker of vascular lineage, more sensible and specific than CD34, WT1, FVIII, and it is almost always negative in non-vascular neoplasms, such as mesotheliomas and carcinomas." (PMID 28810922, 2017). "Furthermore, we considered the possibility of a cutaneous malignant vascular neoplasm, but again the vascular markers including ERG, CD31, and CD34, were all negative." (PMID 35639915, 2022).